MSH6 (mutS homolog 6)
Diseases named in the same sentence as MSH6 in open-access papers (continued):
Sharing a sentence is not in itself a finding about the gene and the disease.
glioblastoma (continued). "In glioblastoma, MSH6 mutations or loss of expression have been associated with tumor progression during TMZ treatment and ensuing TMZ resistance, but the role of MSH6 in clinical melanoma is less well characterized." (PMID 30274152, 2018). "Although patients with biallelic mutations in MSH6 have been reported with the CMMRD phenotype, including lymphomas, glioblastomas, astrocytomas and café-au-lait spots, our patient only had CRC at the age of 41 and a sister with colangiocarcinoma at the age of 44." (PMID 26437257, 2015). "Importantly, for the remaining nine PGVs that were identified in genes with a strong association with familial glioblastoma or medulloblastoma (SUFU, MSH6 (2x), PMS2 (5x) and BRCA1), a second (somatic) event and/or a matching mutational signature was identified in the tumor." (PMID 41168197, 2025). "Although numbers remain small, a higher-than expected frequency of patients with glioblastoma carrying a PGV in MMR genes was seen, with the biggest difference for MSH6 and PMS2." (PMID 41168197, 2025). "On the other hand, acquired hypermethylation of mismatch repair genes MSH6, LTBP4, and ALKBH5 are almost exclusively observed in recurrent glioblastoma post-initial treatment." (PMID 38928445, 2024). "Further interrogation has revealed the differential expression of MGMT and MSH6 between the subtypes, which suggested the involvement of distinct mechanisms for TMZ resistance during recurrence of glioblastomas." (PMID 26466313, 2015). "Deficiency in MSH6 has been found to cause resistance to TMZ and tumor progression irrespective of MGMT status in glioblastoma and in aggressive pituitary adenomas or carcinomas." (PMID 28900805, 2017).
pancreatic cancer (33 papers, 2016 to 2026). "MSH6 was significantly associated with pancreatic cancer (P = 0.029) and all-cancer groups (P = 0.023; women: P = 0.044)." (PMID 36896836, 2023). "APC, BRCA2, BUB1B, ENG and MSH6 were associated with cancer predisposition, and pathogenic/likely pathogenic (P/LP) variants occurred in 6% [pancreatic cancer (4/72); all-cancer (5/90)] and 54% (49/90) carried only variants of uncertain significance (VUS) among cancer patients." (PMID 36896836, 2023). "P/LP variants of APC, BRCA2, BUB1B and ENG were identified in patients with pancreatic cancer, and MSH6 was identified in an NPaMC patient with both colorectal and esophageal cancers." (PMID 36896836, 2023). "Tier I or II mutations related to hereditary cancer syndrome in pancreatic cancer were identified in BRCA1 (n = 2, 2.3%), BRCA2 (n = 2, 2.3%), PRSS1 (n = 1, 1.1%), MSH6 (n = 2, 2.3%), PMS2 (n = 1, 1.1%), and APC (n = 1, 1.1%)." (PMID 36463295, 2022). "Consistent with our results, MSH6 rs1042821 has previously been associated with increased CRC risk, highly malignant bladder cancer, pancreatic cancer and triple negative breast cancer (TNBC)." (PMID 31374908, 2019). "They found that haplotypes of O6-methylguanine-DNA methyltransferase (MGMT), MSH6, PMS1 Homolog 2 (PMS2), PMS2-like 3 (PMS2L3), and tumour protein 73 (TP73) were significantly associated with an increased pancreatic cancer risk (P = 0.0015)." (PMID 29069866, 2017).
pancreatic cancer (continued). "In agreement with this, our cohort and TCGA studies demonstrated that KIF11 expression in pancreatic tumor tissues was indeed positively correlated with GIN markers, including MSH6, aneuploidy score, and fraction of genome altered." (PMID 34208606, 2021).
Familial adenomatous polyposis (29 papers, 2009 to 2025). Familial adenomatous polyposis (FAP) is characterized by the development of hundreds to thousands of adenomas in the rectum and colon during the second decade of life.
mismatch repair deficiency (29 papers, 2011 to 2025). "Although constitutional DNA was not available for testing, this patient's clinical history is consistent with an inherited MMR deficiency such as Turcot's syndrome, associated with germline MSH6 mutation." (PMID 21637783, 2011). "In addition, we identified pathogenic variants on which we have already reported in detail, in DICER1 in Case-10 diagnosed with DICER1 syndrome and in MSH6 in Case-7 who has a constitutional mismatch repair deficiency." (PMID 33840814, 2021). "Interestingly, one patient with 186 VUS had a presumptive history of neurofibromatosis type 1 (NF1) based on cutaneous stigmata but was found instead to have congenital mismatch repair deficiency (CMMRD) with an MSH6 mutation." (PMID 31827999, 2019). "The sixth case, the only known constitutional mismatch repair deficiency (CMMR-D) patient in Estonia, had compound-heterozygous variants in MSH6 gene." (PMID 37509324, 2023). "Most of Hannibal’s mutations are likely a consequence of mismatch repair deficiency, given that Hannibal has missense variants in MLH1 and MSH6 genes, and/or clock-like mutational processes." (PMID 35557512, 2022). "The tumor was hypermutated (56.7 somatic mutations per Mb), showed the mutation signature of mismatch repair deficiency, and had MSH‐2 and MSH‐6 protein losses as determined by immunohistochemistry." (PMID 28145097, 2017).
mismatch repair deficiency (continued). "MSH6 was absent in one pediatric MSI-High tumor, consistent with an inherited mismatch repair deficiency associated with germline MSH6 mutation." (PMID 21637783, 2011).
adenoma (23 papers, 2015 to 2025). A neoplasm arising from the epithelium. "Elevated adenoma burden has been shown in about 6% of LS patients, and multiple cumulative adenomas are particularly observed in carriers of pathogenic MSH6 and PMS2 gene variants as well as individuals with CMMRD." (PMID 38725616, 2024). "A third of MSI-H adenomas showed MLH1 promoter hypermethylation while a further third of such adenomas showed loss of MSH6 (and could be part of LS)." (PMID 33922305, 2021). "Information on dMMR crypts and dMMR adenomas incidences in path_MSH6 and path_PMS2 carriers is limited." (PMID 38741120, 2024). "In our study, we found that the LOE of MMR proteins was mainly distributed in MSH-2 and MSH-6 in 6 adenomas by MMR IHC detection in 508 inpatients with adenomas." (PMID 30918532, 2019). "Moreover, it has been reported that MSH6 and PMS2 mutation carriers can benefit more from colonoscopy surveillance since MMR-DCF are both less common and less likely to progress along the adenoma–carcinoma sequence." (PMID 34201893, 2021). "Therefore, the MSH6 frameshift variants in these two families could be not explain the onset of all cancers and/or adenomas, as other different genetic variants could be responsible for the LS phenotype observed in these families." (PMID 28481244, 2017). "Although small case series evaluated the MGMT status prior to TMZ treatment in aggressive adenomas and pituitary carcinomas, a systematic evaluation of MGMT and MSH6 status in functioning pituitary macroadenomas has not been performed thus far." (PMID 28900805, 2017).
melanoma (22 papers, 2009 to 2025). A malignant, usually aggressive tumor composed of atypical, neoplastic melanocytes. "A previous study showed that increased MSH6 expression was significantly associated with an increased risk of melanoma mortality." (PMID 28387323, 2017). "In line with our study, high expression of MSH6 was significantly associated with poor survival rates in melanoma and osteosarcoma." (PMID 29046615, 2017). "Our findings of this signature in a patient harboring several MSH6 mutations, but not among dacarbazine-exposed patients without mutations, may indicate DNA mismatch repair defects to play a role in melanoma as well." (PMID 29991680, 2018).